CD4 (CD4 molecule)
Diseases named in the same sentence as CD4 in open-access papers (continued):
Sharing a sentence is not in itself a finding about the gene and the disease.
tumor (continued). "Low‐risk patients exhibited higher infiltration of favorable immune subsets, such as plasma cells, naïve B cells, and resting memory CD4+ T cells, whereas high‐risk patients exhibited a tumor‐promoting immune signature, enriched for M1/M2 macrophages and CD8+ T cells." (PMID 41584726, 2026). "SPP1 was found to be associated with angiogenesis score in CD4+ T cells, which may be involved in tumour progression." (PMID 39231761, 2025). "In addition, Opg has been implicated in the regulation of CD4+ T cell infiltration into the tumor microenvironment." (PMID 40772227, 2025). "Additionally, lower counts of CD4+ T helper cells limit the activation of effector immune cells, causing inadequate immune response signaling and a tumor microenvironment unresponsive to immune efforts aimed at attacking the tumor." (PMID 41155343, 2025). "Immunological analyses reveal a marked reduction in the infiltration levels of CD8+ T cells, NK cells, tumor-infiltrating lymphocytes, CD4+ T cells, and follicular helper T cells in the high-risk group, accompanied by a general downregulation of immune functions." (PMID 40496857, 2025). "Additionally, CD39 expression, a marker of pathogenic T cells, was elevated in the tumor areas in both CD4+ and CD8+ T cells." (PMID 40547009, 2025). "Similarly, activated CD4+ T cells secrete IFNγ + EVs to enhance STING activation in tumor-associated macrophages, reprogramming them toward a pro-inflammatory phenotype and eventually amplifying the efficacy of STING-based cancer immunotherapies." (PMID 40400306, 2025). "Analysis of effector activity of these tumor-infiltrating CD4+ T cells revealed that T-bet-deficient CD4+ T cells had markedly impaired functionality in both saline and M002 treatment groups, as the IFNγ+TNFα+ population and the expression of GzmB were significantly reduced." (PMID 39885128, 2025). "Naïve CD4+ and CD8+ T cells as well as CD4+ and CD8+ T cells with a SLEC phenotype were significantly associated with each other, indicating that the LN tumor microenvironment (TME) is similarly influencing the differentiation of these cell states both in CD4+ and CD8+ T cells." (PMID 40775219, 2025). "Furthermore, the combination of OX40 co-stimulation or CTLA-4 blockade with melanoma-specific CD4+ T cell therapy achieves comprehensive tumor elimination, including targeting antigen escape variants." (PMID 40661781, 2025). "Considering the role of cytotoxic CD4+ T cells in tumor surveillance, we suggest that suppression of senescent CD4+ T cells may contribute to the increased cancer risk in RA patients under permissive conditions." (PMID 41235706, 2025). "Compensatory immune pathways, particularly CD8+ T-cell cytotoxicity and NK cell-mediated antibody-dependent cellular cytotoxicity (ADCC), may overcome CD4+ deficiency to contribute to tumor regression." (PMID 40969752, 2025). "Its high expression is associated with increased CD4+ T lymphocyte infiltration, which may affect the tumor immune microenvironment." (PMID 40717587, 2025). "Importantly, functional deficiencies in CD8+ cytotoxic T lymphocytes (CTLs), CD4+ Th1 helper T cells, or natural killer (NK) cells are associated with increased tumor incidence." (PMID 41375025, 2025). "TBC1D10C is a selective, constitutive suppressor of the CD8 T-cell antitumor response, and the Tbc1d10c–Map3k3–NF-κB signaling axis is a viable therapeutic target to promote CD8 T-cell antitumor immunity while circumventing CD4 T cell-associated cytotoxicity and NF-κB activation in tumor cells." (PMID 40761790, 2025). "Their expansion correlates inversely with splenic Breg activity (r=-0.72, P < 0.01) and parallels tumor-associated CD4+CD8a+ T cells that modulate CD8+ T cells via TGF-β1/PD-1 signaling, suggesting conserved immunosuppressive mechanisms across inflammatory contexts." (PMID 40709179, 2025).
tumor (continued). "By comparing samples with available tumor stage information, we found that diffuse gastric cancer exhibited notably higher proportions of endothelial cells, macrophages, and cancer-associated fibroblasts, along with lower proportions of CD4+ and CD8+ T cells." (PMID 41584584, 2025). "We then wondered if there was any relationship between tumor burden, evaluated as number of circulating neoplastic cells at T1, expressed as percentage of clonal CD4+TCRVβ+ calculated within total CD4+ T cells, and the number of persistent mutated genes found in each patient." (PMID 40918137, 2025). "Although higher CD4+ count may be linked to lower mortality, the relationship between tumor features on histopathology and tumor behavior still remains unclear." (PMID 41281090, 2025). "As an effect, the naïve T cell differentiation towards the pathogenic CD4+ Th17 lineage reflects the positive feedback mechanism between immune-responsive and modulatory subsets that intensifies inflammatory responses and the process of tumor development." (PMID 41376623, 2025). "Given that stem-like CD4+ T cells give rise to diverse effector and dysfunctional populations, we focus on their differentiation fates to understand the mechanisms underlying tumor control and immune evasion." (PMID 40634636, 2025). "Other cell populations, including CD4+ helper T cells, B-lymphocytes, and tumor-associated macrophages, also contribute to the modulation of immune responses and may influence PD-L1 expression patterns." (PMID 41296438, 2025). "High density of CD4+ T cells at the tumor edge also seems to be associated with good DFS and OS." (PMID 40070825, 2025). "We hypothesize that the increased tumor signal enhancement in MT218-MRMI following immunotherapy may be associated with additional EDB-FN secretion by activated CD4+ and CD8+ T cells." (PMID 41041061, 2025). "Notably, FAw3byFA increased effector memory CD4+ T cells, implicated in tumor progression, with mediation analysis attributing ~10% of CRC risk to this pathway—potentially via T-cell exhaustion." (PMID 40990012, 2025). "Tumor cell vaccines use the patient’s tumor cells (autologous) or allogeneic cell lines that contain the antigens associated with tumors and, thus, the epitopes of CD4+ helper T-cells and CD8+ CTLs." (PMID 40006583, 2025). "And the decrease in CD4 counts was linked to tumor progression." (PMID 40475019, 2025). "Notably, PD‐1 expression in CD4+ tumor‐infiltrating lymphocytes (TILs) is associated with greater BC invasiveness." (PMID 41049266, 2025). "Then, through keyword clustering and a timeline view, we found that the latest research can be divided into eight modules: the enteric nervous system, gut microbiota, cardiolipin, microbiota-gut-brain axis, tumor-associated monocytes and CD4(+) T cells, central nervous system, and community." (PMID 40822852, 2025). "In addition, the RBC-MoSe2 combined with 808 nm laser irradiation and PD-1 checkpoint-blockade exhibited higher tumor ablation through CD4+ T cells activation in primary tumor and reprogramming the tumor-associated macrophages to tumoricidal M1 phenotype." (PMID 40017598, 2025). "Activated DCs phagocytose tumor-associated antigens (TAAs) and present them to CD4+ and CD8+ T cells via major histocompatibility complex (MHC) molecules, promoting T cell proliferation, differentiation, and effector functions, thereby eliciting a specific antitumor immune response." (PMID 41451226, 2025). "Immune populations, including CD8+ cytotoxic and CD4+ helper T cells, regulatory T cells, B cells, NK cells, dendritic cells, tumor-associated macrophages, neutrophils, and myeloid-derived suppressor cells, modulate both anti- and pro-tumor immunity." (PMID 41511309, 2025).
tumor (continued). "The results showed that cells with antitumor effects, such as CD4+ T cells, NK cells, monocytes, and plasma cells, were negatively associated with the HCCEvoSig risk score, whereas cells with pro-tumor functions, such as macrophages and neutrophils, were positively correlated." (PMID 40901047, 2025). "However, there is also emerging preclinical data highlighting the concern that concurrent ENI with tumour irradiation mitigates these systemic and local immune responses, specifically due to effects associated with effector CD4 and CD8 T cells." (PMID 40677085, 2025). "Notably, we found a close relationship between mitochondrial-associated genes in CRC and tumor-infiltrating immune cells, including plasma cells, resting CD4 memory T cells, activated CD4 memory T cells, resting dendritic cells, and eosinophils." (PMID 40290445, 2025). "Low levels of CD4 T lymphocytes are associated with tumor recurrence." (PMID 40352665, 2025). "Alterations in specific CD8+ and CD4+ T-cell subpopulations during neoadjuvant chemoimmunotherapy may favor better outcomes and are potentially associated with tumor hypoxia." (PMID 41230345, 2025). "Considering these findings, we speculate that CTLs antigen recognition becomes compromised due to B2M mutation/deletion, while other immune cells such as CD4+ T lymphocytes, NK cells, and γδ T cells may continue to exert cytotoxic effects on tumor cells." (PMID 40191187, 2025). "To test whether increased T cells might be causally involved in tumor suppression in young mice, we depleted CD4+ or CD8+ T cells in young mice." (PMID 41332581, 2025). "Thus, KLRG1 is a diagnostic marker for isolation and further study of tumor-matching, cytotoxic CD4+ T cell clones from the periphery of patients with cancer." (PMID 40299576, 2025). "This apparent paradox can be explained by the more profound reduction in CD8+ T cells, likely due to their heightened susceptibility to exhaustion in the tumor microenvironment, coupled with a relative expansion of immunosuppressive CD4+ T‐cell subsets, such as regulatory T cells (Tregs)." (PMID 41404191, 2025). "In addition, LAMTOR1, also known as p18, is a type of lysosome‐associated membrane protein, modulates MHC‐II expression on tumour cells via the endocytic pathway, influencing CD4+ T cell‐mediated recognition and subsequent CD8+ T cell antitumour response." (PMID 40673641, 2025). "For instance, Transporter Associated with Antigen Processing 1 (TAP1)/ATP-Binding Cassette Subfamily B Member 2 (ABCB2) deficiency has been linked to increased CD8+ T cells and decreased tumor-associated neutrophils and CD4+ regulatory T cells, enhancing anti-PD-1 responses." (PMID 40445912, 2025). "Rfwd3 knockdown caused an increase in the number of tumor‐infiltrating CD4+ and CD8+ T cells." (PMID 41117130, 2025). "Collectively, our preclinical data, consistent with the clinical results, pointed to a critical contribution of CD4+ T cells associated with the MHCII upregulation on tumor cells and intratumoral immune cells to GBM control and patient survival after oHSV therapy." (PMID 39885128, 2025). "These revealed that in addition to CD3 + T cells, IgE treatment was associated with significantly increased CD8+ T cells in tumor, stromal, and necrotic areas, while CD4+ T cell infiltration was significantly increased in tumor areas, as compared to PBS controls." (PMID 39934835, 2025). "In addition, the elevated infiltration of CD8 T cells, CD4 T cells, and NK cells in the tumor microenvironment (TME) is linked to improved patient’s prognosis." (PMID 41185082, 2025). "Conversely, the increased presence of CD4 memory resting cells in the low‐risk group may reflect a more balanced immune environment, potentially enhancing immune surveillance and tumor control." (PMID 40116585, 2025).
tumor (continued). "Additionally, tsMHC-II-presented tumor neoantigens have more stable mutations, suggesting that tsMHC-II and CD4 + T cells play a more deep-seated role in anti-tumor immune surveillance than previously thought." (PMID 40495188, 2025). "It has been shown that MHC class II is essential for the activation of CD4 + T cells and its deficiency might contribute to an exhausted phenotype of tumor-reactive CD8 + T cells." (PMID 40676060, 2025). "Furthermore, the association between high NTRK3 expression with low CD4+ T cell infiltration and poorer prognosis emphasizes the importance of the tumor-immune interaction in BC progression." (PMID 40142285, 2025). "rMDV encoding L-Meq (vRB-1B_L-Meq) exhibited higher mortality and tumor incidence than rMDV encoding Meq (vRB-1B_Meq), and vRB-1B_L-Meq infection increased the proportion of CD4+ T cells, which are targets for transformation by MDV, in the early post-infection phase, compared with vRB-1B_Meq." (PMID 40673706, 2025). "High-risk patients exhibited higher proportions of pro-tumor immune cells (M0 macrophages, M2 macrophages, and dendritic cells) and lower proportions of anti-tumor immune cells (M1 macrophages, CD4+ memory T cells, and CD8+ T cells) compared to low-risk patients." (PMID 40781483, 2025). "While CD4+ T-helper cell infiltration is associated with improved prognosis in node-negative cases, further research is necessary to clarify the role of Tregs and other immune components in the tumor microenvironment." (PMID 41007768, 2025). "Low levels of CD4 T lymphocytes are linked to an increased risk of tumor recurrence." (PMID 40352665, 2025). "The tumor suppressor Menin, prone to mutations in both hereditary and sporadic endocrine tumors, along with its direct target Bach2, plays a crucial role in preventing autoimmunity by regulating CD4 + T cell senescence and maintaining cytokine homeostasis." (PMID 40128849, 2025). "Immune infiltration analysis showed that RELT was significantly associated with immune cells such as B Cells, CD8+ T Cells, CD4+ T Cells, and Macrophages and may affect the tumor immune microenvironment of ccRCC by influencing macrophages." (PMID 41376629, 2025). "Its expression may be induced by inflammatory cytokines such as IFN-γ and TNF-α secreted by tumor-infiltrating lymphocytes and is associated with increased CD4+ T-cell infiltration." (PMID 40940814, 2025). "Initially, its role as a pro-inflammatory cytokine serves to eliminate tumor antigens; however, as the cancer progresses, the polarization of naïve CD4+ T-helper cells towards pathogenic Th17 lineage releases IL-17 and also IL-6 cytokines that are important to advance tumor stage and development." (PMID 41376623, 2025). "These clonal dynamics, coupled with subset-specific interactions (e.g., tumor-associated atypical B cells with CD4+ T cells via MHC-II), shape B cells’dual roles in humoral immunity and T cell regulation, with implications for antitumor immunity, immune evasion, and immunotherapy response." (PMID 41246318, 2025). "This association suggests that an increased tumor cell proliferation may correspond to a greater presence of CD4+ follicular T cells in luminal B tumors." (PMID 39858472, 2025). "Indeed, cDC2s are crucial promoters of CD4+ T helper cell responses via the presentation of MHCII‐associated tumor antigens." (PMID 40667699, 2025). "By analyzing the immune characteristic within the TME, we found a reduction in the infiltration of anti-tumor immune cells in the high-risk group, such as CD8+ T cells, NK cells, tumor-infiltrating lymphocytes, CD4+ T cells, and T follicular helper cells (all p<0.001)." (PMID 40496857, 2025). "However, evidence for pro-tumour development comes from the association of CD4+ Foxp3+ Tregs with poor clinical outcomes." (PMID 40351814, 2025).
tumor (continued). "We defined a total of six conserved and distinct “cellular neighborhoods (CN)” and one unique spatial architecture with CD8+ T and CD4+ T cell-enriched neighborhoods leads to less proximity of CD8+ T cells to the tumor cells associated with shorter overall survival (OS)." (PMID 38611111, 2024). "Compared to the low-risk group, the high-risk group had a higher proportion of most tumor immune cells, including initial B cells (p < 0.001), dormant CD4 memory cells (p = 0.0081), dormant natural killer cells (p = 0.145), M1-type macrophages (p = 0.0014), and M2-type macrophages (p < 0.001)." (PMID 38240702, 2024). "Notably, the positive correlation of the risk score with resting NK cells, activated CD4+ memory T cells, and activated mast cells suggests a complex interplay between these immune components and tumour progression in NSCLC." (PMID 38973477, 2024). "Detailed analysis of this region shows that PVMs are at the center of these interactions and are closely associated with not only the tumor endothelial cells, but also multiple immune populations, including liver-resident CD4+ and CD8+ T cells, macrophages, and dendritic cells." (PMID 39761010, 2024). "In low-risk patients, the tumor microenvironment is characterized by a substantial infiltration of immune cells, including CD4 T cells and CD8 T cells, which are classified as tumor-infiltrating lymphocytes (TILs), as well as a notable presence of M2 macrophages and DCs." (PMID 38756785, 2024). "The analysis revealed high expression of Th2 cells, natural killer T cells, macrophage cells, iTreg cells, cytotoxic cells, NK cells, Tr1 cells, central memory cells, CD4 T cells, and Tfh cells in most tumors, indicating a potential association with tumor progression." (PMID 38714855, 2024). "Using granulocyte-macrophage colony-stimulating factor (GM-CSF) as an adjuvant, the naked mRNA vaccine targeting several tumour-associated antigens slowed the progression of renal cancer with the induction of both CD4+ and CD8+ T cells responsive to the antigens in some patients in a clinical trial." (PMID 38528828, 2024). "Alternatively, a recent study proposed that CD4+ T cells may remotely induce inflammatory cell death and subsequently shift tumor-associated myeloid cells toward tumoricidal effector phenotypes." (PMID 38824567, 2024). "Similar to the published reports, the congenital deficiency of CD11chi DCs reduced the proportion of CD4+Foxp3+ Treg cells in lymphoid tissues under homeostatic and tumor-bearing conditions, suggesting the importance of CD11chi DCs in the maintenance of the population size of CD4+Foxp3+ Treg cells." (PMID 39206204, 2024). "In pathological situations like tumor development, which happens slowly inside the organ, homeostatic adaptations may cause changes in CD4+ T lymphocyte composition." (PMID 38690280, 2024). "Moreover, we found that DRGs expression was also differentially increased in several important TIICs involved in tumor suppressive immunity, such as CD4+ T cells and tumor-associated macrophages (TAMs)." (PMID 39091494, 2024). "A small number of studies with murine cancers had already identified the epitopes recognized by CD8+ and CD4+ T cells that were mutated in cancers and were thus cancer specific; indeed, one could immunize mice with these peptides and elicit tumor rejection." (PMID 38426497, 2024). "We conclude that this vaccine combination is associated with antigen-specific immunological responses and can generate activated hTERT-specific CD4+/CD8+ effector responses against this tumour associated antigen in patients with therapy-resistant solid tumours." (PMID 38463391, 2024). "Enhanced Th2 immune response, certain components of Th2-driven inflammation in cancer, may be associated with the antitumor activity of CD4 Th2 cells and tumor-infiltrating granulocytes, especially regulatory eosinophils." (PMID 39024248, 2024).